FNDC8 (fibronectin type III domain containing 8)
Synonyms: DKFZp434H2215
Tractability: No criterion of Open Targets' tractability assessment is met for any kind of drug.
Gene: Protein-coding gene on chromosome 17 (35,121,615 to 35,130,732, forward strand). Ensembl gene ENSG00000073598.
Subcellular location (Human Protein Atlas): Cytosol
Gene Ontology:
Molecular function: protein binding
Biological process: spermatid development
Cellular component: nucleus; non-collagenous component of interstitial matrix; perinuclear theca
Genetic constraint (gnomAD): Loss-of-function variants: 23 observed, 25.73 expected, observed/expected ratio (o/e) 0.89, 90% interval 0.64 to 1.27. The upper end of that interval is the gene's LOEUF score, 1.27, which puts it in group 5 of 6, group 1 being the genes least tolerant of losing a copy. Missense variants: 371 observed, 416.9 expected, observed/expected ratio (o/e) 0.89, 90% interval 0.82 to 0.97. Synonymous variants: 158 observed, 173.76 expected, observed/expected ratio (o/e) 0.91, 90% interval 0.8 to 1.04.
Homologues: Orthologues: chimpanzee FNDC8 (99% identical), macaque FNDC8 (94% identical), dog FNDC8 (79% identical), rabbit FNDC8 (78% identical), pig FNDC8 (77% identical), guinea pig FNDC8 (73% identical), mouse Fndc8 (66% identical), rat Fndc8 (66% identical).
Diseases named in the same sentence as FNDC8 in open-access papers:
FNDC8 is named in the same sentence as 13 diseases in open-access papers, as found by Europe PMC text mining. Sharing a sentence is not in itself a finding about the gene and the disease. The quoted sentences say what the papers report.
liver cancer (2 papers, 2022 to 2023). An epithelial or non-epithelial malignant neoplasm that arises from the liver. "Additionally, compared to normal liver tissues, FNDC3A and FNDC4 showed lower expression, while FNDC3B and FNDC8 displayed higher expression in liver cancer." (PMID 36626432, 2022). "With respect to liver cancer, high expression of FNDC1, FNDC3A, FNDC5, and FNDC7 was correlated with better prognosis, but increased expression of FNDC6 and FNDC8 was correlated with poor OS and PFS, respectively." (PMID 36626432, 2022).
lobular breast cancer (1 paper, 2022). "FNDC8 was decreased in ductal breast cancer in situ, invasive ductal and lobular breast cancer, and invasive mixed breast carcinoma in studies from TCGA database." (PMID 36626432, 2022).
lung adenocarcinoma (1 paper, 2022). A carcinoma that arises from the lung and is characterized by the presence of malignant glandular epithelial cells. "However, in lung adenocarcinoma, all members of the FNDC family, except FNDC7 and FNDC8, are interrelated to RFS/OS and FP." (PMID 36626432, 2022). "Furthermore, the whole FNDC family, except for FNDC7 and FNDC8, was found to have substantial predictive effects in lung adenocarcinoma, but not in squamous cell lung cancer." (PMID 36626432, 2022).
ovarian carcinoma (1 paper, 2022). A malignant neoplasm originating from the surface ovarian epithelium. "Except for FNDC8, high expression of the FNDC family members was associated with poor prognosis in ovarian cancer patients." (PMID 36626432, 2022).
cancer (3 papers, 2022 to 2024). A tumor composed of atypical neoplastic, often pleomorphic cells that invade other tissues. "Oncomine revealed that the mRNA expression levels of FNDC1, FNDC3A, and FNDC3B were higher in most malignancies than in normal tissues, but the mRNA expression levels of FNDC4, FNDC5, FNDC7, and FNDC8 were downregulated in most cancers when compared with normal tissues." (PMID 36626432, 2022).
FNDC8 also shares sentences with these, for which no sentence is quoted: and Central Nervous System cancer (1 paper); breast carcinoma (1); cervical cancer (1); colon adenocarcinoma (1); gastric cancer (1); melanoma (1); squamous cell lung carcinoma (1); tumor (1).